APOB (apolipoprotein B)
Diseases named in the same sentence as APOB in open-access papers (continued):
Sharing a sentence is not in itself a finding about the gene and the disease.
Stroke (93 papers, 2009 to 2026). Sudden impairment of blood flow to a part of the brain due to occlusion or rupture of an artery to the brain. "Our study showed that a higher apoB/apoAI ratio is independently associated with ICAS in young stroke patients, after careful exclusion of alternative arteriopathies and adjustment for confounders." (PMID 42256577, 2026). "A total of 16 biomarkers have been found to exhibit significant causal relationships with stroke, namely ApoB, LDL-C, CHO, HbA1c, HDL-C, Lp(a), TG, ApoA, UA, DB, TP, calcium, GLU, AST, ALA, Crea, and gamma-glutamyl transferase (GGT)." (PMID 41282433, 2025). "Our MR analysis also confirmed a causalrelationship between ApoB and cardiovascular diseases, including stroke, coronaryartery disease, heart failure, and peripheral atherosclerosis." (PMID 40475729, 2025). "In multivariate Cox regression, the ApoB/ApoA-I ratio as a continuous variable was an independent risk factor for stroke recurrence (HR 4.007, 95% CI 1.661–9.666, P < 0.001)." (PMID 38274879, 2023). "The addition of ApoB/ApoA-I to the traditional risk model improved the predictive power of the model, implying that ApoB/ApoA-I is a good indicator in predicting stroke recurrence." (PMID 38274879, 2023). "The findings of the current study suggest an association between the ratio of ApoB to ApoA-I measured during the acute phase of the first stroke and the risk of stroke recurrence within 1 year." (PMID 38274879, 2023). "In univariate Cox regression, the risk of stroke recurrence in patients with ApoB/ApoA-I above the median was nearly twice as high as in patients below the median (HR 1.975, 95% CI 1.312–2.973, P < 0.001)." (PMID 38274879, 2023). "Elevated plasma levels of ApoB/ApoA-I are an independent risk factor for stroke recurrence within 1 year of acute ischemic stroke." (PMID 38274879, 2023). "Univariate and multivariate cox regression analyses for the association of ApoB/ApoA-I with stroke recurrence." (PMID 38274879, 2023). "Due to the fact that the pathophysiology, prognosis, and clinical features of small-vessel ischemic strokes are different from other stroke subtypes, the association of ApoB/ApoA-I with small-vessel stroke is uncertain." (PMID 38274879, 2023). "ApoB/ApoA-I ratio, measured during the acute phase of the first stroke, was positively correlated with the risk of stroke recurrence within 1 year." (PMID 38274879, 2023). "In this study, we recruited a cohort with a first diagnosis of ischemic stroke and found that ApoB/ApoA-I was an independent risk factor for stroke recurrence and showed good predictive value." (PMID 38274879, 2023). "Genetically elevated apoB caused higher risks of heart disease in all first-degree relatives and a higher risk of stroke in mothers." (PMID 34729547, 2021). "Mothers of individuals with genetically elevated apoB had a higher risk of stroke (1·05, 1·02–1·08, FDR-adjusted p=4·2 × 10–4)." (PMID 34729547, 2021). "Several studies have indicated an correlation of the ApoB/ApoA1 ratio and the risk of stroke, intracranial and extracranial carotid stenosis." (PMID 32017458, 2020). "The apoB/apoA-I ratio reflects the equilibrium between atherogenic and antiatherogenic lipoproteins in the bloodstream, with a higher ratio being linked to an elevated risk of stroke." (PMID 38978811, 2024). "The identification of the ApoB/ApoA-I ratio as a significant predictor of PSCI could enable better risk stratification of cognitive impairment for stroke patients and provide a target for interventions to prevent PSCI." (PMID 37960323, 2023). "Based on these considerations, we hypothesized that a high ApoB/ApoA-I ratio may be associated with worse cognitive outcomes following stroke." (PMID 37960323, 2023).
Stroke (continued). "Based on current studies, we found that elevated ApoB/ApoA-I levels were associated with stroke recurrence within 1 year after the first acute cerebral infarction, and this association remained statistically significant after adjusting for potential risk factors." (PMID 38274879, 2023). "A positive correlation between the ApoB/ApoA-I ratio and the risk of stroke recurrence within 1 year was demonstrated using Cox regression analysis, which remained significant after adjusting for traditional risk factors [hazard ratio (HR) 4.007, 95% confidence interval (CI) 1.661–9.666]." (PMID 38274879, 2023). "In the multivariable logistic regression analysis, the highest quintile (Q5) of the ApoB/ApoA-I ratio was found to be significantly associated with the development of PSCI at 3 to 6 months after stroke compared with Q1 (adjusted odds ratio [aOR], 3.00; 95% CI, 1.10–8.20)." (PMID 37960323, 2023). "The ethnic difference in the impact of the ApoB/ApoA1 ratio on stroke risk may be related to genetics or metabolism." (PMID 34082746, 2021). "Increased apoB levels are specifically associated with earlier onset of first-ever atherothrombotic stroke; moreover, a high apoB/apoA-I ratio is described as a risk factor for this stroke subtype and it is increased in unstable plaques." (PMID 33153204, 2020). "Secondly, long term follow-up for the morbidity of ischemic stroke in non-stroke group was required to further prove that high level of apoB/AI ratio might increase the risk of ischemic stroke through accelerating ICAS." (PMID 31479420, 2019). "Another study found that oxLDL influence the incidence of stroke, and rs676210 in ApoB gene associated with oxLDL, so rs676210 loci may affect the incidence risk of stroke." (PMID 29416768, 2018). "The APOBECs may affect stroke risk through effects on APOB mRNA editing; however, APOBECs may play additional roles within the brain." (PMID 23365789, 2013). "The pathogenic mechanisms of ApoB and ApoA-I suggest that the ratio represents a balance between pro- and anti-atherosclerotic, pro- and anti-inflammatory, and thrombotic and antithrombotic lipoprotein particles and has great clinical application in stroke risk assessment and targeted therapy." (PMID 38274879, 2023). "The study found that apoB/A1 substantially outperformed the LDL-C/HDL-C ratio, with each standard deviation rise linked to a 38% increased risk of stroke." (PMID 40863347, 2025). "A large-scale study on Chinese individuals found a negative correlation between plasma HDL and the risk of ischemic stroke, a weak positive correlation between TG levels and stroke risk, and a strong correlation between LDL and apolipoprotein B levels." (PMID 39540824, 2024). "Genetically predicted levels of ApoB/ApoA1 and M-HDL-C were more strongly associated with CHD than HF or stroke." (PMID 38724583, 2024). "For the multivariable MR analyses, we fitted a model with apolipoprotein B and LDL cholesterol to identify which one or more traits appeared to be responsible for the effect of lipid-related traits on risk of stroke." (PMID 37528862, 2023). "The SMR method was conducted to assess the association between the expression of HMGCR, PCSK9, NPC1L1, and APOB and stroke outcome." (PMID 37528862, 2023). "The purpose of this study was to clarify the prognostic value of ApoB/ApoA1 for stroke recurrence and alleviate future cerebrovascular disease." (PMID 38274879, 2023). "IVW-MR association between LDL cholesterol mediated by gene HMGCR, PCSK9, NPC1L1, or APOB and stroke and its subtypes." (PMID 37528862, 2023). "The serum ApoB/ApoA-I concentrations on admission were significantly higher in patients with stroke recurrence at 1 year compared to those with good prognosis (median 1.01 mmol/L vs. 0.84 mmol/L, P < 0.001)." (PMID 38274879, 2023). "The aim of this study was to investigate the prognostic value of ApoB/ApoA-I for stroke recurrence within 1 year after the first incident." (PMID 38274879, 2023).
Stroke (continued). "Serum ApoB/ApoA-I concentrations on admission were higher in patients with stroke recurrence at 1 year compared with those with a good prognosis (P < 0.001)." (PMID 38274879, 2023). "SMR association between expression of gene HMGCR, PCSK9, NPC1L1 or APOB and stroke and its subtypes." (PMID 37528862, 2023). "Multiple variants in the SLCO1B1, PRIM1, APOB, TYK2, TSEN15, CYP4F2, and MST1 genes were previously suggested as risk factors for stroke with p-values < 1.0 × 10−5 in a GWAS on German pediatrics." (PMID 37895268, 2023). "This study found that the highest quintile of the ApoB/ApoA-I ratio was associated with a three-fold increased risk of developing PSCI, reinforcing the potential role of this lipid imbalance in post-stroke cognitive outcomes." (PMID 37960323, 2023). "The Kaplan-Meier survival curve revealed a significant difference in cumulative stroke recurrence rates across ApoB/ApoA-I tertiles (log-rank P-value < 0.001)." (PMID 38274879, 2023). "The reasons for the difference between the two types of stroke related to BMI are unclear, although the authors see it in an increased apolipoprotein B/A1 ratio in people with abnormal BMI." (PMID 35566778, 2022). "A Mendelian Randomisation (MR) study showed that ApoB is the predominant trait in the relationship of lipoprotein lipids with the risks of heart disease and stroke." (PMID 36247924, 2022). "Jong‐Ho Park also suggested that a higher ApoB/ApoA1 ratio is a predictor of intracranial atherosclerotic stenosis in Asian patients with stroke (Park, Hong, Lee, Kim, & Song, 2013)." (PMID 32017458, 2020). "After adjusting these covariates, the apoB/AI ratio (OR 2.80, 95%CI 1.45-5.42, p =0.002) was demonstrated to be an independent risk factor for ICAS against a background of stroke." (PMID 31479420, 2019). "The present study expanded previous researches via observing the association of apoB/AI and ICAS in stroke patients and meanwhile comparing the same indicators in non-stroke controls for contrast." (PMID 31479420, 2019). "Available evidence shows that ApoB-100 encloses all atherogenic lipoproteins and is a reliable predictor, together with the ApoB/ApoA1 ratio, of CVD and stroke risk." (PMID 28704936, 2017). "In addition to plasma lipoprotein levels, the concentrations of some of their components, such as apolipoproteins, including apoB, apoA-I, and apoC-III, has been associated with atherothrombotic stroke." (PMID 39746448, 2024). "Therefore, it is necessary to explore the relationship between ApoB/ApoA-I and different stroke subtypes." (PMID 38274879, 2023). "Subgroup analysis of odd ratios of ApoB/ApoA-I for stroke recurrence." (PMID 38274879, 2023). "A future line of research on the discussed topic would be to study the relationship and relevance of the predictive value of ApoB/ApoA-I for recurrence within 1 year after the first incident stroke in ischemic small-vessel disease vs. other ischemic stroke subtypes." (PMID 38274879, 2023). "Moreover, in the INTERSTROKE study (n = 13,447 patients with stroke and 13,472 controls from 32 countries), 26.8% of strokes were due to an increased apoB/ApoA1 ratio." (PMID 35076490, 2021). "In summary, increased apoB/AI ratio was a valuable independent risk factor for ICAS in stroke patients as well as in non-stroke controls." (PMID 31479420, 2019). "The apoB/AI ratio has the same value in non-stroke controls." (PMID 31479420, 2019). "Increased ratio of apoB/AI was an independent risk factor for ICAS in both stroke group (OR 2.80, 95% CI 1.45-5.42, p=0.002) and non-stroke groups (OR 3.38, 95% CI 1.61-7.12, p<0.001)." (PMID 31479420, 2019). "There is still little research on the effect of ApoB gene on stroke in Chinese Han population." (PMID 29416768, 2018).
Stroke (continued). "ApoB level has been shown to be significantly higher in stroke patients compared to controls." (PMID 29245986, 2017). "ApoB/ApoA1 was associated with MI and stroke, but not HF in the observational analysis." (PMID 38724583, 2024). "According to the subgroup analyses in this study, we also found that a high ApoB/ApoA-I ratio was strongly associated with an increased risk of stroke recurrence regardless of whether the patients had high or low LDL-C levels." (PMID 38274879, 2023). "Subgroup analysis further revealed that a high ApoB/ApoA-I ratio was strongly associated with stroke recurrence regardless of whether patients had high or low LDL-C levels." (PMID 38274879, 2023). "Taken together, our findings show that reductions in apoB should be the primary goal of lipid lowering, because not only does this lead to lower risk of common diseases such as heart disease and stroke, but also a reduction in apoB prolongs life by a period of months to years." (PMID 34729547, 2021). "The current study demonstrated that the apoB/AI ratio was an independent risk factor for ICAS in both stroke and non-stroke Chinese individuals, suggesting the effects of apoB/AI ratio on increasing the risk of ICAS were the same between stroke and non-stroke individuals." (PMID 31479420, 2019). "While it has been suggested that ApoB and ApoA-I may play a more influential role in CVD prevention than total LDL and HDL, further research is needed to understand the optimal indicators of effective lipid-lowering treatment in patients at risk for stroke." (PMID 20028534, 2009). "Based on the Gene Expression Omnibus (GEO) database analysis, significant differences in the expression levels of LIPC, APOB, CETP, PNPLA2, and LMF1 between the control and stroke groups were observed." (PMID 37273686, 2023). "Consequently, an elevated ApoB/ApoA-I ratio, which signifies a state of enhanced inflammation, oxidation, and atherogenesis, could potentially augment neuronal damage subsequent to a stroke, thereby precipitating cognitive impairment." (PMID 37960323, 2023). "Our bioinformatics analysis results indicated that the expression levels of LIPC and its related genes (APOB, CETP, PNPLA2, and LMF1) showed significant differences between stroke and control groups." (PMID 37273686, 2023). "With this background, the decrease in ApoB and PCYOX1 observed in HT-treated stroke patients could be considered as indicative of an atheroprotective effect of HT." (PMID 38732018, 2024). "For stroke, only several M-HDL traits and ApoB/ApoA1 were found significant." (PMID 38724583, 2024). "Univariate Cox regression revealed that history of stroke, creatinine (Cr), left ventricular ejection fraction(LVEF), TG, HDL, TC/HDL, ApoB, ApoA1/ApoB, Fg, pulmonary artery pressure (PAP), high GS group, TVD, and PCSK6 rs1531817 genotypes were associated with the occurrence of MACEs." (PMID 39039525, 2024). "The restricted cubic spline plot did not reveal a non-linear relationship between serum ApoB/ApoA-I and 1-year stroke recurrence (P = 0.402 for non-linear trend)." (PMID 38274879, 2023). "The interaction analysis showed that stratified subgroups (including LDL cholesterol) did not have an interaction effect with ApoB/ApoA-I on stroke recurrence." (PMID 38274879, 2023). "RCS regression indicated that among subjects with normal hs-CRP, ApoB displayed a non-linear pattern with stroke, TC and LDL-C displayed a non-linear pattern with CHD, and ApoB displayed a non-linear pattern with CHD and CVD (all P < 0.05)." (PMID 37403063, 2023). "Firstly, the lack of available eQTLs in blood for NPC1L1 and APOB limited our ability to explore the association between NPC1L1 and APOB expression in blood and stroke." (PMID 37528862, 2023). "Increased hs-CRP interacted negatively with elevated LDL-C on the risk of stroke, with low HDL-C, ApoAI, and ApoB on the risk of CHD, and with high LDL-C and non-HDL-C on the risk of CVD." (PMID 37403063, 2023).
Stroke (continued). "The follow-up LDL-C (as well as TC or ApoB) levels in patients stroke+ were lower than in subgroup without this condition (stroke-)." (PMID 35368707, 2022). "ApoB, apoA-1, and the apoB/apoA-1 ratio were analysed in relation to MACEs (non-fatal MI, stroke, and cardiovascular [CV] mortality), yielding 22,473 events." (PMID 34851955, 2021). "Notably, the multivariable Mendelian randomization analysis showed that apoB is the main factor responsible for the apoB, LDL, and TGs-related strokes (p < 0.005)." (PMID 34067469, 2021). "An additional study has supported the clinical utility of oxidized phospholipids-APOB as a biomarker for the prediction of recurrent fatal or nonfatal stroke, which have augmented proinflammatory responses and enhanced uptake of monocytes into the vessel wall." (PMID 32508734, 2020). "Recently, a study found that acute ischemic stroke patients with ICAS have a higher ApoB/AI ratio was meaningfully higher than those without ICAS in both stroke group and non-stroke groups." (PMID 32622367, 2020). "This study was the first to report that APOB and APOC-I levels were significantly increased in CAD as compared to stroke subjects, indicating that the dysregulation of lipid metabolism may play an important role in the pathophysiology of CAD." (PMID 32508734, 2020). "ApoB/AI ratio of patients with ICAS was significantly higher than those of individuals without ICAS in both stroke group and non-stroke groups." (PMID 31479420, 2019). "Furthermore, genetic variants in PLCB4/PLC1 have been significantly associated with several phenotypic traits including levels of apolipoprotein B, cholesterol and HDL, along with body weight, body mass index and stroke." (PMID 26434682, 2015). "One year after the onset of the stroke, an improved lipid profile was observed, because although TAG and VLDL cholesterol remained similar, patients exhibited higher concentrations of HDL-C, lower concentrations of TC and LDL-C, and lower LDL-C/HDL-C and apoB/apoA-I ratios." (PMID 39746448, 2024). "However, there is a lack of research into the correlation between ApoB/ApoA1 and stroke recurrence after the first episode." (PMID 38274879, 2023). "Furthermore, bioinformatics analysis results demonstrated that the expression levels of LIPC and its related genes (APOB, CETP, PNPLA2, and LMF1) were significantly different between the control and stroke groups (p < 0.05), and LIPC-related proteins were mainly related to lipid metabolism." (PMID 37273686, 2023). "The tests of interactions between HDL-c, LDL-c and apoB/AI ratio appeared non-significant results (In stroke group, HDL-c p for interaction=0.246, LDL-c p for interaction=0.517; In non-stroke group, HDL-c p for interaction=0.774, LDL-c p for interaction=0.211)." (PMID 31479420, 2019). "In addition, the apolipoprotein-B-(ApoB-) editing catalytic subunit (APOBEC) family of RNA editing and DNA recoding enzymes may also play a role in stroke." (PMID 23365789, 2013). "The results showed that individuals with ICAS had higher apoB and lower apoAI compared to those without ICAS in both stroke and non-stroke groups." (PMID 31479420, 2019). "We carried out the present study to examine whether this similar relationship between apoB/AI ratio and ICAS could be established amongst the stroke and non-stroke individuals in Chinese population." (PMID 31479420, 2019). "However, other evidence suggests ApoB rather than LDL-C is the key lipid in IHD and stroke." (PMID 33924871, 2021).